CPNE9 (copine family member 9)
Description:
Probable calcium-dependent phospholipid-binding protein that may play a role in calcium-mediated intracellular processes (By similarity). Plays a role in dendrite formation by melanocytes.
Synonyms: KIAA4217
Tractability: Antibody: its Gene Ontology location is reachable by antibodies, with medium confidence; the Human Protein Atlas places it where antibodies can reach. PROTAC: ubiquitination databases record sites on it.
Gene: Protein-coding gene on chromosome 3 (9,703,691 to 9,729,908, forward strand). Ensembl gene ENSG00000144550.
Subcellular location (Human Protein Atlas): Cytosol; Plasma membrane
Gene Ontology:
Molecular function: calcium-dependent phospholipid binding
Biological process: positive regulation of dendrite extension; cellular response to calcium ion
Cellular component: extracellular exosome; extracellular region
Genetic constraint (gnomAD): Loss-of-function variants: 56 observed, 81.09 expected, observed/expected ratio (o/e) 0.69, 90% interval 0.56 to 0.86. The upper end of that interval is the gene's LOEUF score, 0.86, which puts it in group 3 of 6, group 1 being the genes least tolerant of losing a copy. Missense variants: 607 observed, 724.94 expected, observed/expected ratio (o/e) 0.84, 90% interval 0.78 to 0.89. Synonymous variants: 248 observed, 276.28 expected, observed/expected ratio (o/e) 0.9, 90% interval 0.81 to 1.
Homologues: Orthologues: chimpanzee CPNE9 (100% identical), macaque CPNE9 (99% identical), pig CPNE9 (99% identical), rat Cpne9 (99% identical), mouse Cpne9 (99% identical), guinea pig CPNE9 (98% identical), rabbit CPNE9 (92% identical), dog CPNE9 (84% identical), tropical clawed frog cpne5 (83% identical), zebrafish cpne9 (71% identical), Caenorhabditis elegans gem-4 (46% identical), Caenorhabditis elegans nra-1 (46% identical), and 2 more. Paralogues in human: CPNE5 (78% identical), CPNE8 (76% identical), CPNE3 (48% identical), CPNE4 (48% identical), CPNE7 (48% identical), CPNE2 (47% identical), CPNE6 (46% identical), CPNE1 (45% identical).
Diseases named in the same sentence as CPNE9 in open-access papers:
CPNE9 is named in the same sentence as 4 diseases in open-access papers, as found by Europe PMC text mining. Sharing a sentence is not in itself a finding about the gene and the disease. The quoted sentences say what the papers report.
glioblastoma (1 paper, 2021). The most malignant astrocytic tumor (WHO grade IV). "Moreover, CPNE9 was among the top five genes of the prognostic 14-gene signature that was used to construct the prognostic model that demonstrated a high predictive ability for glioblastoma." (PMID 34367247, 2021).
Intellectual disability (1 paper, 2022). "For example, breakpoints of a 12 kb copy neutral inversion identified in monozygotic twins suffering from intellectual disability disrupt genic regions of BRPF1 and CPNE9." (PMID 35484572, 2022).
multiple myeloma (1 paper, 2021). "Recent research found that high CPNE5 and CPNE9 expression might serve as positive indicators of multiple myeloma, and the expression of both genes was a better predictor of survival in multiple myeloma patients." (PMID 34367247, 2021).
cancer (1 paper, 2021). A tumor composed of atypical neoplastic, often pleomorphic cells that invade other tissues. "A study by Liu found that CPNE9 is specifically expressed in pancreatic tumor tissues, indicating that CPNE9 is related to cancer progression." (PMID 34367247, 2021).